PPARG (peroxisome proliferator activated receptor gamma)
Diseases named in the same sentence as PPARG in open-access papers (continued):
Sharing a sentence is not in itself a finding about the gene and the disease.
endometrioid adenocarcinoma (1 paper, 2020). An adenocarcinoma characterized by the presence of malignant glandular epithelial cells resembling endometrial cells. "Moreover, PPARγ expression was higher in endometrioid adenocarcinoma (n=409) than in serous carcinoma (n=115, P<0.001)." (PMID 33197888, 2020).
enteritis (1 paper, 2022). Inflammation of the small intestine. "In CD animal models, increased levels of PPARγ can directly exert anti‐inflammatory effects and thereby mitigate enteritis." (PMID 35707871, 2022).
eosinophilic esophagitis (1 paper, 2024). Eosinophilic esophagitis (EoE) is a chronic, allergic disease of the esophagus characterized clinically by symptoms of esophageal dysfunction (including vomiting, dysphagia, feeding disorders, food impaction and abdominal pain) which persist after treatment with proton pump inhibitors (PPIs). "In isolated fibroblasts and biopsies from the esophagi of patients with eosinophilic esophagitis (EoE), PPARγ expression was higher in active EoE than in inactive EoE and healthy controls." (PMID 39451206, 2024).
Era (1 paper, 2022). "Correspondingly, the role of H3K27me2 and H3K27me3 in Era induced a decrease in PPARγ and C/EBPα expression." (PMID 35202251, 2022).
falciparum malaria (1 paper, 2014). "We also observed the same neuroprotective pathways induced in patients with falciparum malaria that received PPARγ adjunctive therapy." (PMID 24603727, 2014).
Fanconi anemia (1 paper, 2021). Fanconi anemia (FA) is a hereditary DNA repair disorder characterized by progressive pancytopenia with bone marrow failure, variable congenital malformations and predisposition to develop hematological or solid tumors. "Other involved pathways were again cell cycle signaling (15%, CDK6, CDK12), Fanconi anemia/DNA repair (15%, FANCD2, NBN), and additionally peroxisome proliferator-activated receptor (PPAR) signaling (8%, PPARG) as well as discoid in domain receptor 2 signaling (8%, DDR2)." (PMID 34200508, 2021).
femoral neck fracture (1 paper, 2019). Fractures of the short, constricted portion of the thigh bone between the femur head and the trochanters. "Western blot analysis showed that ONFH patients in the traumatic ONFH group (P = 0.045), steroid-induced ONFH group (P < 0.001), and alcohol-induced ONFH group (P < 0.001) had significantly higher PPARγ protein expression than those in the femoral neck fracture group." (PMID 31886265, 2019).
fungal infection (1 paper, 2010). "Interestingly, we had established that the expression of these two receptors was increased by IL-13 through the activation of the nuclear receptor PPARγ, suggesting that PPARγ could be a therapeutic target to eliminate fungal infection." (PMID 20062524, 2010).
gallbladder cancer (1 paper, 2025). "Furthermore, PPARγ expression has been identified in gallbladder cancer, and its occurrence is intricately linked to the PPARγ target." (PMID 41403929, 2025). "Anticancer efficacy of a novel PPARγ agonists based on the glycyrrhetic acid scaffod (PG-4c) was evaluated in gallbladder cancer in vivo and vitro." (PMID 41403929, 2025). "Taken together, these results highlight PG-4c as a promising low-toxicity PPARγ-targeted compound for gallbladder cancer therapy." (PMID 41403929, 2025). "In this study, we evaluated the antitumor activity of a novel PPARγ agonist, PG-4c, in gallbladder cancer and assessed its in vivo toxicity." (PMID 41403929, 2025). "PG-4c could be a new PPARγ lead-candidate agonist and potentially used for gallbladder cancer treatment." (PMID 41403929, 2025).
gastritis (1 paper, 2008). Inflammation of the stomach. "In several models of gastritis or gastric ulcers, activation of PPARγ attenuates mucosa damage and accelerates healing, via reduction of inflammation, apoptosis, and lipid peroxidation." (PMID 19125181, 2008).
hemangiosarcomas (1 paper, 2008). "Whilecarcinogenicity is less of a concern for PPARγ agonists than for PPARα or α/γ dual agonists, the two most prevalenttypes of tumors associated with PPARγ full agonist molecules which do occur are lipomasand hemangiosarcomas." (PMID 18769500, 2008). "Similarly, the lack of edema in preclinical models suggestsa weak activity in the vascular endothelium and thus would be unlikely to invokethe activation associated with hemangiosarcomas at very high doses of full PPARγ agonists." (PMID 18769500, 2008).
hepatocellular adenoma (1 paper, 2021). A benign epithelial neoplasm arising from the hepatocytes. "In hepatocellular adenoma (HCA) and a subset of HCC, the expression and activity of PPARG is significantly increased, affecting metabolic rearrangements and liver tumorigenesis via the transcriptional regulation of hexokinase 2 (HK2) and M2 pyruvate kinase (PKM2)." (PMID 34771521, 2021).
HIV encephalitis (1 paper, 2013). "Other studies demonstrated the ability of PPARγ agonists to inhibit HIV replication in vitro or in animal models of HIV encephalitis by acting on macrophages." (PMID 24359430, 2013).
Hodgkins lymphoma (1 paper, 2023). A heterogeneous group of malignant lymphoid neoplasms of B-cell origin characterized histologically by the presence of Hodgkin and Reed-Sternberg (HRS) cells in the vast majority of cases. "For example, in r/r cholangiocarcinoma, r/r Hodgkin’s lymphoma (HL) with a principally weak PPARγ expression, cCR may be achieved with editing schedules including pioglitazone, in contrast, in r/r non-small cell lung cancer with commonly relative intensive expression, only partial remission." (PMID 38273846, 2023).
Hydrocephalus (1 paper, 2022). Hydrocephalus is an active distension of the ventricular system of the brain resulting from inadequate passage of CSF from its point of production within the cerebral ventricles to its point of absorption into the systemic circulation. "PPARγ agonists enhanced myelination, reduced inflammation and hydrocephalus, and promoted neurological recovery in newborns with intraventricular hemorrhage (IVH)." (PMID 35720361, 2022).
Hyperkeratosis (1 paper, 2012). Hyperkeratosis is a histopathological term defining a thickened stratum corneum and may be present in many different skin conditions, with many possible overlaps. "Although Pparγ is a direct transcriptional target of Nrf2, Pparβ/δ is more likely to be the isoform involved among the three Ppar isoforms because Pparβ/δ agonists were known to cause terminal differentiation of keratinocytes in vitro and dermal hyperkeratosis in vivo." (PMID 22567161, 2012).
hyperphosphatemia (1 paper, 2019). Abnormally high level of phosphate in the blood. "Treatment of VSMCs with phosphate as well as hyperphosphatemia in a CKD mouse model showed a downregulation in the expression of PPARγ and its downstream target Klotho." (PMID 31698866, 2019).
hypersplenism (1 paper, 2024). Overactive functioning of the spleen, resulting in excessive destruction of blood cells. "The expression of SCARB1, ALOX15, STAT6, and IL4 was up-regulated in hypersplenism, while the PPARγ expression was down-regulated." (PMID 39620221, 2024). "In this study, the results of patients with hypersplenism showed that the c-Myc regulatory alternative activation pathway dependent genes by upregulation of IL-4 mediated signal transduction to participate in M2-like polarization and downregulation of PPARγ and IFN-γ gene expression." (PMID 39620221, 2024).
hypopharyngeal cancer (1 paper, 2023). Carcinoma, predominantly squamous cell, arising from the epithelial cells of the hypopharynx.
idiopathic dilated cardiomyopathy (1 paper, 2024). Decreased function of the heart associated with cardiac enlargement and congestive heart failure, of unknown cause. "miR-130b-3p has been shown to be downregulated in the plasma of idiopathic dilated cardiomyopathy patients, but its role in modulating cardiomyocyte lipotoxicity via PPARγ remains unclear." (PMID 39596228, 2024).
inclusion body myositis (1 paper, 2026). A slowly progressive degenerative inflammatory disorder of skeletal muscles characterized by late onset weakness of specific muscles and distinctive histopathological features. "This single-arm, open-label phase 1 trial evaluated the PPARγ agonist pioglitazone in patients with inclusion body myositis (IBM)." (PMID 41832158, 2026).
Kashin-Beck disease (1 paper, 2022). Disabling osteochondrodysplasia with osteosclerosis, cone-shaped metaphysis, and shortening of the diaphysis. "A recent study demonstrated that genetic polymorphisms of PPARG might promote the risk of the Kashin-Beck disease via disturbing ECM homeostasis." (PMID 36544567, 2022).
laryngeal carcinoma (1 paper, 2025). Carcinoma that arises from the laryngeal epithelium. "But the actual functional roles of PPARG playing in laryngeal cancer are still lack of investigation." (PMID 40183093, 2025).
Lymphadenopathy (1 paper, 2020). Enlargement (swelling) of a lymph node. "Gross examination of MLN indicated lymphadenopathy in both wild-type and PPARγ KO mice instilled with MWCNT+ESAT-6 compared to vehicle control." (PMID 32405439, 2020).
metastasis (1 paper, 2024). The spread or migration of cancer cells from one part of the body (where they first appeared) to another. "High PPARG expression was significantly associated with pulmonary metastasis (p = 0.019)." (PMID 38378472, 2024).
microcephaly (1 paper, 2018). A congenital or acquired developmental disorder in which the circumference of the head is smaller than normal for the person's age and sex. "What they found is that NesCre/PPARγ-WT mice displayed severe microcephaly and brain malformation, indicating that PPARγ can control brain development." (PMID 29949869, 2018).
minimal change disease (1 paper, 2022). "SAA combined with prednisone exhibited therapeutic and antiproteinuric effects on adriamycin-induced minimal change disease rat model through PPARγ/Angptl4 and Nrf2/Heme oxygenase-1 (HO-1) pathways." (PMID 35528835, 2022).
mucinous ovarian cancer (1 paper, 2026). An invasive malignant neoplasm that arises from the ovary and is characterized by the presence of malignant epithelial cells that contain intracytoplasmic mucin and may resemble the epithelial cells of the endocervix or gastrointestinal tract. "We then performed cis drug-target MR for PPARG, DPP4, ABCC8/KCNJ11, and SLC5A2, integrated triangulation, colocalization, and mediation analyses, and experimentally interrogated the prioritized PPARG/ABCC8-KCNJ11-lactate-invasive mucinous ovarian cancer (IMOC) triangle." (PMID 42278567, 2026).
multinodular goiter (1 paper, 2015). Nodular goiter characterized by more than one discrete tissue mass. "Since PPARγ and TG exhibited at least a 3-fold downregulation and little variability in multinodular goiter PTC samples, compared to their benign counterparts from the same subjects, these genes might represent additional valuable candidates for the here presented combined predictive score." (PMID 25868389, 2015). "Separate analysis of a subset of the multinodular goiter samples with more aggressive PTC subtypes revealed 2 - 4-fold upregulation in the levels of CHEK1, c-MET and TIMP1, and a 2-4-fold downregulation of BCL2, c-KIT, TG and PPARγ (lower part)." (PMID 25868389, 2015).
Multiple Organ Failure (1 paper, 2025). A progressive condition usually characterized by combined failure of several organs such as the lungs, liver, kidney, along with some clotting mechanisms, usually postinjury or postoperative. "IL17A, IL1B, MBL, and NOD2 were also reported to be associated with mortality, and PPARG was associated with multiple organ failure in our study." (PMID 40168842, 2025).
myelofibrosis (1 paper, 2023). A partial or complete replacement of the bone marrow stroma by fibrous tissue. "In the case of PPARG, it has been extensively linked to MPNs, since its ligands promote the resolution of myelofibrosis in preclinical models and seem to be crucial for the development of new therapeutic approaches for hematological malignancies." (PMID 36611979, 2023).
myxoid chondrosarcoma (1 paper, 2017). A chondrosarcoma characterized by the presence of myxoid changes. "The EWSR1 (EWS RNA binding protein 1)/NR4A3 fusion protein of extraskeletal myxoid chondrosarcoma activates PPARγ which is crucial for lipid metabolism regulation." (PMID 28800357, 2017).
myxoid/round cell liposarcoma (1 paper, 2022). Myxoid/round cell liposarcoma (MRCLS) is a type of liposarcoma (LS) mostly located in the limbs, with a variable behavior depending on the histological subtype. "PPARγ has been considered more related to the other LPS type, myxoid round cell liposarcoma (MRCLS)." (PMID 36557266, 2022).
myxoma (1 paper, 2022). A benign soft tissue neoplasm characterized by the presence of spindle and stellate cells, lobulated growth pattern, and myxoid stroma formation. "The clinical results of the experiment confirmed that miR-122-dependent downregulation of MEF2D by PPARg suppresses the proliferation of myxoma cells, suggesting that PPARg may exert its antiproliferative effects by negatively regulating the MEF2D." (PMID 35328730, 2022).
non-Hodgkin lymphoma (1 paper, 2023). Distinct from Hodgkin lymphoma both morphologically and biologically, non-Hodgkin lymphoma (NHL) is characterized by the absence of Reed-Sternberg cells, can occur at any age, and usually presents as a localized or generalized lymphadenopathy associated with fever and weight loss. "As one of oxidative stress genes, PPARG increases the generation of reactive oxygen species appears to increase the risk for non-Hodgkin lymphoma, particularly DLBCL." (PMID 37976136, 2023).
oral mucositis (1 paper, 2020). Inflammation of the mucous membranes of any of the structures in the mouth. "Indeed, pharmacological stimulation of PPARγ exerts beneficial activity in oral mucositis." (PMID 32560286, 2020).
Ovarian cyst (1 paper, 2021). The presence of one or more cysts of the ovary. "Our study indicated that PPARG in the PPAR signaling pathway may be under the regulation of Jingshu granules for ovarian cyst treatment." (PMID 33623786, 2021).
ovarian disease (1 paper, 2021). "In addition, four ovarian DEGs (ABCA5, ADIPOQ, ITGAV, and PPARG) in the FM_1-vs-NM_1 group are associated with negative regulation of macrophage-derived foam cell differentiation and are all involved in ovarian disease." (PMID 35052428, 2021).
ovarian serous adenocarcinoma (1 paper, 2025). An adenocarcinoma that arises from the ovary and is characterized by the presence of malignant epithelial cells that, in well differentiated tumors, resemble the epithelium of the fallopian tube or, in poorly differentiated tumors, show anaplastic features and marked nuclear atypia. "The results revealed that FA metabolism regulators including FABP4, FABP5, and PPARγ are involved in biological aspects in two EOC cell lines, AMOC-2 cells established from ovarian serous adenocarcinoma (OSC) and ES2 cells established from OCCC." (PMID 40429934, 2025).
ovarian serous cystadenocarcinoma (1 paper, 2023). A malignant serous cystic epithelial neoplasm arising from the ovary. "The results indicated lower PPARG expression levels in nine types of cancer, including LUSC, ovarian serous cystadenocarcinoma (OV), BRCA, CESC, HNSC, SKCM, THCA, UCEC, and uterine carcinosarcoma (UCS)." (PMID 38044948, 2023).
periapical granuloma (1 paper, 2021). Chronic nonsuppurative inflammation of periapical tissue resulting from irritation following pulp disease or endodontic treatment. "MCODE-1 with the highest significance for nuclear receptor transcription pathway and the highest PPI in periapical granuloma was between RXRA, PPARG, ESR1, ESRRA, and NR0B1 proteins." (PMID 34539639, 2021).
peroxisome disorders (1 paper, 2022). "1, 11-Undecanedicarboxylic acid and phytic acid may indicate peroxisome disorders, Peroxisome proliferator-activated receptor γ (PPARγ) has been shown to regulate lipid and glucose homeostasis, cell differentiation, and growth regulation." (PMID 35571892, 2022).
pharyngeal squamous cell carcinoma (1 paper, 2022). A squamous cell carcinoma that arises from the pharynx. "Studies have shown that PPARG may increase the chemical sensitivity of pharyngeal squamous cell carcinoma." (PMID 35341150, 2022).
pharyngitis (1 paper, 2020). Inflammation of the throat most often caused by viral and bacterial infections. "DC, CC, and BC analysis indicated that ALB (serum albumin), PPARγ (peroxisome proliferator-activated receptor gamma), MAPK3 (mitogen-activated protein kinase 3), EGF (epidermal growth factor), and PTGS2 (prostaglandin G/H synthase 2) are closely related to pharyngitis." (PMID 33101439, 2020).
placental disorders (1 paper, 2021). "PPARγ activity can be used as a therapeutic option in the treatment and prevention of placental disorders." (PMID 34884974, 2021).
Polyuria (1 paper, 2010). An increased rate of urine production. "PPARγ agonists alter the density of CFTR expression in the plasma membrane but do not interfere with the action of vasopressin on water transport or cause polyuria as observed with vasopressin V2 receptor antagonists." (PMID 21052534, 2010).
pregnancy disorder (1 paper, 2009). A disorder that is related to pregnancy. "Elucidating cellular and molecular mechanisms mediating PPARγ action will help determine if modulating PPARγ activity, for which clinical pharmacologic agonists already exist, might modify the course of pregnancy disorders associated with placental dysfunction." (PMID 19956639, 2009).
pulmonary TB (1 paper, 2023). "Within this setting, we here provide novel evidence that PBMC from newly diagnosed patients with pulmonary TB has an increased expression of PPARγ transcript, related to the degree of lung involvement, proinflammatory plasma mediators, and cortisol levels." (PMID 37187471, 2023).
Reflux Esophagitis (1 paper, 2022). "As a result of this experiment, it was confirmed that SC treatment activated the PPARγ/RXR pathway and increased the expression of antioxidant enzymes such as SOD-1 and catalase in reflux esophagitis." (PMID 35027935, 2022).
Renal atrophy (1 paper, 2018). Atrophy of the kidney. "Previous studies showed that PPARγ activation by telmisartan exhibited renal protective action in mice with renal atrophy and fibrosis and this prevention by telmisartan is associated with a significantly increased renal HGF expression but attenuated by GW966237." (PMID 30089804, 2018).
respiratory syncytial virus infections (1 paper, 2025). "Strategic regulation of PPARG expression might enable a response to pathogens and help prevent respiratory syncytial virus infections, which are often associated with atopy." (PMID 41516283, 2025).
SARS-CoV infection (1 paper, 2021). "PPARγ has also been shown to be downregulated upon SARS-CoV-2 infection in intestinal organoids (GSE149312) and SARS-CoV infection in airway epithelium (GSE47961)." (PMID 34407143, 2021).
Sciatica (1 paper, 2021). Pain in the lower back and hip radiating in the distribution of the sciatic nerve. "In the model of sciatica rats treated with piperine, the expression of NF-kB1 was down-regulated, and the expression of PPARG was up-regulated." (PMID 32130644, 2021). "The results showed that Piper longum L. can regulate the development of sciatica and affect the expressions of PPARG and NF-kB1 through its active ingredient piperine, and there is endogenous interaction between PPARG and NF-kB1." (PMID 32130644, 2021).
Senile plaques (1 paper, 2022). Senile plaques are extracellular deposits of amyloid in the gray matter of the brain. "In addition, ECH significantly reduced the deposition of senile plaques in the brain and decreased the expression of BACE1 in APP/PS1 mice through activating PI3K/AKT/Nrf2/PPARγ pathway." (PMID 35665898, 2022).